SPOCK3 (SPARC (osteonectin), cwcv and kazal like domains proteoglycan 3)
Description:
May participate in diverse steps of neurogenesis. Inhibits the processing of pro-matrix metalloproteinase 2 (MMP-2) by MT1-MMP and MT3-MMP. May interfere with tumor invasion.
Synonyms: TICN3; testican-3; HSAJ1454; TES-3
Tractability: Antibody: its Gene Ontology location is reachable by antibodies, with high confidence; UniProt places it where antibodies can reach, with medium confidence; UniProt predicts a signal peptide or a membrane-spanning region. PROTAC: its protein half-life has been measured.
Gene: Protein-coding gene on chromosome 4 (166,733,384 to 167,234,796, reverse strand). Ensembl gene ENSG00000196104.
Subcellular location: Secreted, extracellular space, extracellular matrix
Pathways (Reactome):
Extracellular matrix organization: Activation of Matrix Metalloproteinases
Gene Ontology:
Molecular function: calcium ion binding; metalloendopeptidase inhibitor activity
Biological process: negative regulation of cell motility; regulation of cell-substrate adhesion
Cellular component: extracellular matrix; gel phase of interstitial matrix
Genetic constraint (gnomAD): Loss-of-function variants: 16 observed, 37.32 expected, observed/expected ratio (o/e) 0.43, 90% interval 0.29 to 0.65. The upper end of that interval is the gene's LOEUF score, 0.65, which puts it in group 2 of 6, group 1 being the genes least tolerant of losing a copy. Missense variants: 294 observed, 336.08 expected, observed/expected ratio (o/e) 0.87, 90% interval 0.79 to 0.96. Synonymous variants: 130 observed, 123.57 expected, observed/expected ratio (o/e) 1.05, 90% interval 0.91 to 1.22.
Homologues: Orthologues: chimpanzee SPOCK3 (99% identical), macaque SPOCK3 (99% identical), dog SPOCK3 (91% identical), mouse Spock3 (90% identical), rat Spock3 (89% identical), tropical clawed frog spock3 (79% identical), rabbit SPOCK3 (73% identical), guinea pig SPOCK3 (73% identical), pig SPOCK3 (72% identical), zebrafish spock3 (54% identical), Drosophila melanogaster Cow (29% identical), Caenorhabditis elegans test-1 (17% identical). Paralogues in human: SPOCK1 (53% identical), SPOCK2 (46% identical), KIAA1210 (9% identical).
Diseases named in the same sentence as SPOCK3 in open-access papers:
SPOCK3 is named in the same sentence as 17 diseases in open-access papers, as found by Europe PMC text mining. Sharing a sentence is not in itself a finding about the gene and the disease. The quoted sentences say what the papers report.
prostate carcinoma (3 papers, 2017 to 2024). A carcinoma that arises from epithelial cells of the prostate gland. "This study aimed to investigate the effect of SPOCK3 on the malignant progression of prostate cancer and to construct a prognostic model to predict DFS of patients with prostate cancer." (PMID 37563543, 2023). "In recent studies, SPOCK3 was highly expressed in the brain while it was lowly expressed in prostate cancer." (PMID 37563543, 2023). "We attempted to systematically investigate the effect of SPOCK3 on the malignant progression of prostate cancer and to build a prognostic model for predicting DFS in prostate cancer patients in this study." (PMID 37563543, 2023). "GO, KEGG, and GSEA enrichment analysis were used to investigate how SPOCK3 affects the malignant progression of prostate cancer." (PMID 37563543, 2023). "SPOCK3 expression was lower in prostate cancer tissue from the Gleason ≥ 8 group than in the Gleason ≤ 7 group (P < 0.001)." (PMID 37563543, 2023). "Based on ESTIMATE and ssGSEA, the relationship between SPOCK3 and immune cell infiltration in prostate cancer tissue was clarified." (PMID 37563543, 2023). "Forty-one candidates were all down-regulated in the first cohort of them, SPOCK3, SPON1, PTN and TGFB3 were associated with the prognosis of prostate cancer patients." (PMID 29190897, 2017). "SPOCK3 has previously been shown to inhibit prostate cancer cell invasion and migration." (PMID 37563543, 2023). "SPOCK3 is a protective factor for DFS in prostate cancer patients." (PMID 37563543, 2023). "We found that SPOCK3 and SPON1 were significantly associated with prostate cancer patients’ PFS." (PMID 29190897, 2017). "Four genes (SPOCK3, SPON1, PTN and TGFB3) and a micro-RNA were selected for exploring their potential roles in the progression of prostate cancer." (PMID 29190897, 2017). "We found that SPOCK3, SPON1, PTN and TGFB3 were significantly correlated with the progression-free survival (PFS) status of prostate cancer patients." (PMID 29190897, 2017).
schizophrenia (2 papers, 2024). A major psychotic disorder characterized by abnormalities in the perception or expression of reality. "We previously observed decreased SPOCK1 and SPOCK3 mRNA expression in the brain of subjects with schizophrenia, which shares genetic overlap with ASD." (PMID 38355786, 2024).
AIDS (1 paper, 2011). A syndrome resulting from the acquired deficiency of cellular immunity caused by the human immunodeficiency virus (HIV). "In addition to the SNP in DYRK1A we also found associations for rs17519417 in SPOCK3 with time to progression to AIDS." (PMID 21364930, 2011). "Furthermore, there was an association between SNP genotype and progression to AIDS for rs17519417 in SPOCK3 in the MACS (p = 0.012), with the C allele associated with slower progression." (PMID 21364930, 2011).
chordoma (1 paper, 2025). Chordomas are rare malignant tumors arising from embryonic remnants of the notochord in axial skeleton. "The expression analysis identified significant downregulation of SPOCK3, NRK, MYH8, DLK1 and SLN, alongside upregulation of HLA-DQA1, GDA, CXCL11, CXCL9 and ADAMDEC1 in chordomas." (PMID 40386066, 2025).
glioma (1 paper, 2019). A benign or malignant brain and spinal cord tumor that arises from glial cells (astrocytes, oligodendrocytes, ependymal cells). "In contrast, high levels of SPOCK2 could abrogate this inhibition of MMP2 by SPOCK3 and increase the invasiveness of glioma cells." (PMID 31338255, 2019). "In a study of glioma, it was found that SPOCK1 and SPOCK3 could inhibit MT1-MMP-mediated MMP2 activation and inhibit glioma cell invasion by binding to MT1-MMP." (PMID 31338255, 2019).
Obesity (1 paper, 2014). Accumulation of substantial excess body fat. "From the known functions of these genes, GNAL, HELIOS, and SOX5 are directly related to adipose tissue metabolism or obesity, while SLC9A3, SPOCK3, ANXA10, MYLK, and VSNL1 may be indirectly related." (PMID 24962627, 2014).
prostate tumor (1 paper, 2023). "CRISP3 was upregulated; conversely, OGN, SPOCK3, COL4A6, CCBE1, and FLRT3 were downregulated in prostate tumor tissues." (PMID 37251946, 2023).
T-cell leukemia (1 paper, 2014). A malignant disease of the T-lymphocytes in the bone marrow, thymus, and/or blood. "Encoded SPOCK3 protein may play a key role in adult T-cell leukemia by inhibiting membrane-type matrix metalloproteinase activity." (PMID 24962627, 2014).
viral infection (1 paper, 2022). "These four molecules are characteristic of each subtype, including: SEZ6 for autoimmune subtype, SPOCK3 for inflammation, FSD1 for viral infection, and PGC for oxidative stress." (PMID 36713418, 2022).
tumor (9 papers, 2009 to 2024). "SPOCK3 encodes a secreted protein involved in diverse steps of neurogenesis and has been shown to inhibit tumor invasion." (PMID 19737398, 2009). "Research indicated that the protein encoded by SPOCK3 might inhibit the activity of membrane-type matrix metalloproteinases and was identified as a suppressor of tumor invasion." (PMID 29190897, 2017). "Other genes included those that encode members of the proteoglycan family (HAPLN1, SPOCK3) and influence ECM structure in the tumor microenvironment and urotensin 2 (UTS2) which has known roles in regulation of angiogenesis." (PMID 34162930, 2021). "Down-regulation was seen for CNTN1, CXCL13, MAOB, PAGE4, PENK, SPOCK3 in CP compared to NP as well as for HSD17B2, SALL1, TRPA1 for tumor-associated bladder stromal cells compared to normal bladder." (PMID 19737398, 2009). "Moreover, the link between SPOCK3 expression and the immune cells validated the role of SPOCK3 in PCa tumor immunity." (PMID 37563543, 2023). "We investigated the relationship between SPOCK3 expression and the tumor immune system in PCa." (PMID 37563543, 2023). "SPOCK3, also called osteonectin, is a member of the calcium-binding proteoglycan protein family and might mediate its tumor suppressive function in PCa by its suppressive effect on tumor invasion." (PMID 36361816, 2022). "Increased expression of TIMP1, MMP1, AGRN, UNC5A, and ADAMTS4 was observed, while the expression of UNC5C, TINAG, SPOCK3, and ITGA7 was reduced in the normal FHC cells compared to the HCT8 tumor cells." (PMID 39011483, 2024). "Spock3 has been demonstrated of its role as a proteinase inhibitor with an anti-adhesive molecule that may help preserving the integrity of certain extracellular matrices or basal laminae, interfering with tumor invasion and controlling tissue remodeling processes." (PMID 37563543, 2023). "Therefore, our study found that during PCa pathogenesis, the disorganized expression of CRISP3, OGN, SPOCK3, COL4A6, CCBE1, and FLRT3 leads to ECM dysfunction and promotes angiogenesis and tumor development." (PMID 37251946, 2023). "They show opposite functions: SPOCK3 inhibits the activity of membrane-type metalloproteinases (MT-MMPs)—zinc endopeptidases that cleave collagens, proteoglycans, and many other components of ECM, mediating tumor invasion and metastasis." (PMID 33287223, 2020). "Therefore, in cancer disease, SPOCK3 reveals an anti-tumor invasion activity, whereas SPOCK2 reveals a pro-tumor invasion activity." (PMID 33287223, 2020).
cancer (4 papers, 2020 to 2023). A tumor composed of atypical neoplastic, often pleomorphic cells that invade other tissues. "For example, Tff3, Hpse, Slit1, Spon1, Spock1, and Spock3 are associated with increased cancer cell invasion and were upregulated in Rreb1-/-, and Selenbp1 and Serpin6b are tumor suppressor genes that were downregulated." (PMID 33929320, 2021). "SPOCK3 has been linked to the development and progression of several human cancer." (PMID 37563543, 2023).
neurological diseases (1 paper, 2023). "By consulting relevant literature, 6 genes related to neurodevelopmental and neurological diseases (GPC5, CA10, DSCAM, IL1RAPL2, CNTN2, and SPOCK3) were verified by ELISA method." (PMID 37539343, 2023). "Finally, six genes/proteins related to neurodevelopmental and neurological diseases (GPC5, CA10, DSCAM, IL1RAPL2, CNTN2, and SPOCK3) were verified by ELISA." (PMID 37539343, 2023).
SPOCK3 also shares sentences with these, for which no sentence is quoted: infection (1 paper); Intellectual disability (1); melanoma (1); neurodegenerative disease (1); substance abuse (1).